SIRT1 (sirtuin 1)
Diseases named in the same sentence as SIRT1 in open-access papers (continued):
Sharing a sentence is not in itself a finding about the gene and the disease.
prostate carcinoma (continued). "Unlike the other DNA damage repair genes that are acutely active following irradiation, SIRT1 is chronically expressed in irradiated prostate cancer cells." (PMID 29717261, 2018). "SIRT7 interacts with SIRT1 to enhance SIRT1-dependent prostate cancer cell metastatic properties and promotes E-cadherin transcriptional repression." (PMID 30510540, 2018). "SIRT1 was found elevated in leukemia, skin cancer, prostate cancer, and colon cancer, but decreased in colorectal adenocarcinoma." (PMID 30038266, 2018). "The increased SIRT1 expression induces neuroendocrine differentiation of prostate cancer cells by activating the Akt pathway." (PMID 29416748, 2018). "The comparison validated SIRT1 expression was significantly upregulated in prostate cancer samples (p value < 0.0001)." (PMID 29717261, 2018). "On the other hand, genistein has also been demonstrated to inhibit the expression of SIRT1 in prostate cancer cells." (PMID 28425936, 2017). "Resveratrol increases expression of SIRT1 in gastric cancer cells and prostate cancer cells, and in rats and mice with high-fat diet." (PMID 28903430, 2017). "In recent reports, miR-3a has been reported to target SIRT1 to inhibit prostate cancer cell proliferation." (PMID 28445161, 2017). "SIRT1 has been shown to be a positive regulator of EMT in prostate cancer, through its deacetylase activity." (PMID 28994177, 2017). "In prostate cancer, SIRT1 enhances cell migration and metastasis by cooperating with ZEB1 to suppress E-cadherin transcription." (PMID 27528025, 2016). "Studies indicate that SIRT1 is overexpressed in various human malignancies such as breast and prostate cancers." (PMID 27793057, 2016). "In theory, targeting SIRT1 can be utilized in cancer therapy, mostly cell cycle arrest in G1 phase showed promise in prostate cancer with DU145." (PMID 27384994, 2016). "We then examined HPRT mutations in prostate cancer PC3 cells with LSD1, SIRT1, combined LSD1/SIRT1 or scrambled shRNA knockdown." (PMID 27384990, 2016). "In prostate cancer, SIRT1-mediated autophagy plays a role in modulating angiogenesis and cellular senescence, while in human breast adenocarcinoma MCF7 cells, it promoted autophagosome maturation and tumor growth." (PMID 28070138, 2016). "Another study also showed that reducing SIRT1 expression decreases in vitro migration of prostate cancer cells and metastasis in immunodeficient mice, which was largely independent of any general effects of SIRT1 on prostate cancer growth and survival." (PMID 27793039, 2016). "Our data suggest that attenuation of miR-449a promotes the invasive phenotype of the ERG-positive CaP in part by inducing the expression of SIRT1 in prostate cancer cells." (PMID 26988912, 2016). "Meanwhile, it has been reported that sirtuin 1 and H2A.Z deregulation in prostate cancer are reciprocally related, and that impaired sirtuin 1-mediated downregulation of H2A.Z via proteasome-mediated degradation." (PMID 26863632, 2016). "Our study demonstrates the antitumor effect of MSCs-Sirt1 on prostate cancer growth, and shows that the effect is mediated by NK cells and macrophages." (PMID 27764779, 2016). "It was reported in42 that FHL2 inhibits FOXO1 activity in prostate cancer cells by promoting the deacetylation of FOXO1 through SIRT1 on DU145." (PMID 26603105, 2015).
prostate carcinoma (continued). "We also report thatSIRT7 interacts functionally with SIRT1, another member of the sirtuin family that hasbeen shown to promote prostate cancer cell migration and metastasis by repressingE-cadherin expression." (PMID 25923013, 2015). "To understand the importance of our result, we sought to determine the endogenous levels of SIRT1 in multiple cancer cell lines, including prostate cancer." (PMID 26439987, 2015). "Several studies found that SIRT1 expression was up-regulated in various cancers such as leukemia, prostate cancer, skin cancer and colon cancer." (PMID 26318035, 2015). "In accordance with these findings in prostate cancer, melatonin was found to repress, in breast cancer cells, RORα, an effect that causes down-regulation of BMAL1 and SIRT1." (PMID 25310649, 2014). "Thereafter, melatonin was shown to exert an antiproliferative effect in human prostate cancer cell lines and in a mouse prostate adenocarcinoma, in conjunction with inhibition of SIRT1, which was partially reversed by forced over-expression of the sirtuin." (PMID 25310649, 2014). "It has been reported that SIRT1 is upregulated in a spectrum of cancers, including lymphomas, leukemia and soft-tissue sarcomas, prostate cancer, lung cancer, and colon carcinoma via one or more of these targets." (PMID 25522783, 2014). "A previous study has provided strong evidence that Sirt1 is significantly overexpressed to function as a tumor promoter in mouse and human prostate cancer and acute myeloid leukemia." (PMID 24959282, 2014). "In prostate cancer, SIRT1 was shown to enhance cell migration and metastasis by cooperating with EMT transcription factor ZEB1 to suppress E-cadherin transcription." (PMID 25424420, 2014). "Serrano reported that transgenic Sirt mice crossed with PTEN-null mice were observed to develop thyroid and prostate cancer further arguing for a tumor promoting function of Sirt1." (PMID 24088390, 2013). "ZEB1 can also recruit the nicotinamide adenine dinucleotide-dependent HDAC SIRT1 in prostate cancer cells to repress E-cadherin and to induce several EMT markers." (PMID 24216980, 2013). "In agreement with our findings, decreased expression of SIRT1 has been reported in several tumors such as glioblastoma, bladder carcinoma, prostate carcinoma, and various forms of ovarian cancers." (PMID 23805287, 2013). "In prostatic cancer cells Byles and colleagues observed Sirt1 to modulate EMT upon EGF signalling via the induction of the transcription factor ZEB1." (PMID 24088390, 2013). "SIRT1 enhances matrix metalloproteinase-2 expression and tumor cell invasion in prostate cancer cells." (PMID 24223900, 2013). "We found that H2AFZ and SIRT1 were up- and downregulated, respectively, at transcript level in primary prostate cancer and high-grade prostatic intraepithelial neoplasia compared to normal prostatic tissues." (PMID 24127549, 2013). "DHT-induced prostate cancer cellular contact-independent growth is also blocked by Sirt1, providing a direct functional link between Sirt1 and the AR, which is a critical determinant of progression of human prostate cancer." (PMID 21549004, 2011). "It has been shown that Sirt1 is significantly elevated in human prostate cancer, acute myeloid leukemia, and primary colon cancer." (PMID 21549004, 2011). "SIRT1 is up-regulated in poorly differentiated adenocarcinomas, compared with normal counterparts, in three transgenic mouse models of prostate cancer and in human prostate tumor tissues." (PMID 21698133, 2011). "Our recent, unpublished data also shows that SIRT1 plays a role in the silencing of TSG transcription in prostate cancer." (PMID 21566744, 2008). "The proliferation of LNCaP prostate cancer cells was greatly reduced by overexpression of SIRT1 and the effect was similar to suppressing β-catenin itself." (PMID 18414679, 2008).
prostate carcinoma (continued). "Our unpublished data demonstrates that SIRT1 down-regulation in prostate cancer cell lines increases the levels of FOXO3a protein, suggesting a role for deacetylation by SIRT1 in ubiquitin-mediated FOXO3a protein degradation." (PMID 21566744, 2008). "Additionally, lactate promotes the sirtuin 1 (SIRT1)-mediated degradation of T-bet and increases the presence of Tregs, which correlates with heightened aggressiveness in prostate cancer." (PMID 40092297, 2025). "Additionally, an inverse correlation between SIRT1 and miR-34a expression was observed in prostate cancer, which led to drug resistance through the BCL2 pathway." (PMID 40149537, 2025). "SIRT1 has been found to have a dual role in tumor progression, and high SIRT1 expression may promote prostate cancer, pancreatic cancer, melanoma cell invasion, and metastasis." (PMID 38044396, 2024). "From these findings, they inferred that SIRT1 is complicit in prostate cancer carcinogenesis." (PMID 37191417, 2023). "However, SIRT1 overexpression inhibits lipid metabolism in prostate cancer cells by activating AMPK phosphorylation and inhibiting SREBP1 expression and nuclear translocation." (PMID 38189049, 2023). "All the more, such inhibitors could be tested in this topical model or in vitro experiments with prostate cancer cell lines, also with the aim to assess the affect on SIRT1 posttranslational pathways." (PMID 37894275, 2023). "Therefore, inhibition of P2X7R radio-sensitized melanoma, while suppression of ATP storage by targeting CD105 / sirtuin 1 (SIRT1) pathway increased radiosensitivity of prostate cancer cells via G2 cell cycle arrest." (PMID 35836249, 2022). "Additionally, we highlight the available information regarding SIRT1–7 regulation by miRNAs, laying much emphasis on the consequences in the progression of breast and prostate cancer." (PMID 36291902, 2022). "Thus, in this review, we summarize and discuss the current information on the mechanistic roles of sirtuins (SIRT1–7) in breast and prostate cancer." (PMID 36291902, 2022). "Interestingly, the authors further showed that the inhibition of these miRNAs reduces proliferation, increases apoptosis, and reduces migration of PC3 prostate cancer cells, which were abrogated by SIRT1 expression." (PMID 36291902, 2022). "To investigate the underlying mechanisms of sexual dimorphism in the skeletal effects of Sirt1 haplo-insufficiency, we studied sex hormone receptors, as a cross talk between SIRT1 and ERα and AR has been previously reported in the context of breast and prostate cancer, respectively." (PMID 36568088, 2022). "Moreover, a subsequent study confirmed that miR-34a expression is downregulated in prostate cancer tissues compared to normal prostate tissues, and miR-34a expression inhibits the proliferation of PC3 prostate cancer cells by downregulating SIRT1 expression." (PMID 36291902, 2022). "High levels of SIRT1 in AR-positive prostate cancer cell lines repress their multiplication." (PMID 35458763, 2022). "Moreover, using DU145 prostate cancer cells, it was previously demonstrated that SIRT1 deacetylates and deactivates FOXO1 transcription activities." (PMID 36291902, 2022). "This suggests that SIRT1 upregulates MMP2 activity to promote the progression of prostate cancer." (PMID 36291902, 2022). "Mechanistically, AGG stimulates cytoplasmic SIRT1 that in turn, deacetylases LAMP1 (lysosomal associated membrane protein 1) on lysine residues of the cytosolic domain, resulting in lipophagy-mediated senescence in prostate cancer cells." (PMID 35317831, 2022).
prostate carcinoma (continued). "Although this contradiction may be influenced by the cancer stage or context, it provides opportunities for future studies to ascertain the molecules or intermediates in AR signaling that are modulated by SIRT1 in favor of the progression of prostate cancer." (PMID 36291902, 2022). "Additionally, SIRT1 expression has been reported to be upregulated in breast, lung, and prostate cancer, as well as CRC." (PMID 34660182, 2021). "Thus, an increased expression of mir-221 not only decreases the SIRT1 protein level resulting in IR and inflammation in adipocytes but also regulates the prostate cancer progression." (PMID 34199293, 2021). "It was also found that SIRT1 can have an impact on the metastasis of prostate cancer." (PMID 34942940, 2021). "Prostate cancer cells are protected from anti-proliferative effects of melatonin by forced Sirt1 overexpression, proposing that Sirt1 may be a direct melatonin target." (PMID 32943992, 2020). "From in vitro studies, osthole (50 μmol/L) could downregulate silent information regulator 1 (SIRT1) expression in prostate cancer LNCaP cells and enhance the sensitivity to doxorubicin (DOX)." (PMID 32028721, 2020). "Similarly, shRNA mediated SIRT1 knockdown enhanced cell proliferation and reduced autophagy by inhibited phosphorylation of S6K and 4E-BP1 while SIRT1 activation by resveratrol reversed these effects in androgen-responsive prostate cancer cells." (PMID 33330467, 2020). "(i) Regulation of androgen receptors (AR): SIRT1 is able to modulate AR activity via direct deacetylation, leading to inhibition of AR activation, translocation and transcription of AR-dependent genes, for instance in prostate cancer." (PMID 33330467, 2020). "Furthermore, two articles describe CDH1 repression in prostate cancer by ZEB1 binding either to NAD-dependent protein deacetylase sirtuin-1 (SIRT1) or to lysine methyltransferase 5A (SET8)." (PMID 32796736, 2020). "SIRT1 expression is significantly elevated in many solid tumors, such as prostate cancer." (PMID 31598701, 2019). "SIRT1 regulates EMT in prostate cancer cells by interacting with the EMT-TF ZEB1." (PMID 30761005, 2019). "Moreover, the downregulation of SIRT1 attenuates the migration and invasion of prostate cancer cells." (PMID 31817470, 2019). "However, Deng et al31 found that the expression of SIRT1 was lower in prostate cancer, bladder cancer, ovarian cancer, and glioblastoma when compared with normal tissues." (PMID 30697969, 2019). "Thus, SIRT1 acts as a positive regulator of EMT to influence the metastatic growth of prostate cancer cells, while SIRT1 overexpression serves as a potential therapeutic target to reverse EMT and defend against prostate cancer progression." (PMID 31817470, 2019). "Likewise, SIRT1 promotes EMT in prostate cancer cells by cooperating with the EMT-inducible transcription factor ZEB1." (PMID 31817470, 2019). "SIRT1 activation is observed in prostate cancer and in response to irradiation." (PMID 29717261, 2018). "Therefore, we sought to compare SIRT1 levels in patient samples to determine its role in prostate cancer." (PMID 29717261, 2018). "The epigenetic factor SIRT1 can promote prostate cancer progression, but it is unclear whether SIRT1 contributes to neuroendocrine differentiation." (PMID 29416748, 2018).
prostate carcinoma (continued). "Using R2-Genomics analysis, we compared SIRT1 expression in patient samples from the German Cancer Research Center and National Center of Tumor Diseases Affymetrix GeneChip exon array dataset with benign tissue (n = 48) and prostate cancer tissue (n = 47)." (PMID 29717261, 2018). "In prostate cancer cells SIRT1 inhibition sensitized DU145 to cisplatin." (PMID 29100388, 2017). "As a result, loss of SIRT1 decreases prostate cancer cell migration and metastasis, independent of any effects on cell survival." (PMID 28994177, 2017). "Also, SIRT1 is found significantly elevated in human prostate cancer and primary colon cancer implying SIRT1 serves as a tumor promoter." (PMID 28903430, 2017). "SIRT1 is significantly elevated in human prostate cancer and acts as a major epigenetic regulator." (PMID 26988912, 2016). "E-Cadherin, N-cadherin, fibronectin, and γ-catenin were major targets of SIRT1 during the regulation of EMT in prostate cancer cell lines, and the suppression of E-cadherin expression was related to direct modulation of the proximal promoter in an E-box dependent manner." (PMID 27379175, 2016). "In prostate cancer, SIRT1 represses the epithelial morphology through its deacetylase activity." (PMID 27379175, 2016). "Moreover, SIRT1 has been found to promote prostate cancer metastasis by inducing EMT, but to prevent lung cancer metastasis by blocking the EMT." (PMID 27081083, 2016). "In addition, NAMPT is prominently overexpressed along with SIRT1 in human prostate cancer cells and SIRT1 is a key downstream target of NAMPT for prostate cancer cell growth and survival." (PMID 26389889, 2015). "In fact, SIRT1 was found to be over-expressed in prostate cancer tissue." (PMID 25310649, 2014). "For example, Sirt1 was reported to promote cell migration and invasion of prostate cancer." (PMID 25184156, 2014). "The biological impact and regulation of SIRT1 on prostate cancer cells were investigated." (PMID 24892674, 2014). "SIRT1 is overexpressed in human prostate cancer, acute myeloid leukemia, and primary colon cancer." (PMID 25522783, 2014). "Recent reports have indicated that deacetylation of FOXO-1 by SIRT1 could enhance VEGF-C transcription in the nuclei of prostate cancer cells and facilitate the growth of endothelial cells in mice." (PMID 25922660, 2014). "Epigenetic modifying drugs in conjunction with enzymatic modulators are able to restore the normal functions of sirtuin 1 and might constitute relevant tools for targeted therapy of prostate cancer patients." (PMID 24127549, 2013). "We concluded that sirtuin 1 and H2A.Z deregulation in prostate cancer are reciprocally related." (PMID 24127549, 2013). "SIRT1, which may act either as tumor suppressor or oncogene, reduces H2A.Z levels in cardiomyocytes, via proteasome-mediated degradation, and this mechanism might be impaired in prostate cancer cells due to sirtuin 1 downregulation." (PMID 24127549, 2013). "Meanwhile, there are several genes which mediate the miR-34a induced tumor growth inhibition, such as BCL2, E2F3 and MYCN in neuroblastoma, mitogen-activated protein kinase kinase 1 (MEK1) in human chronic myelocytic leukemia cell line K562 and SIRT1 in prostate cancer PC3 cells." (PMID 22457788, 2012). "In the case of prostate cancer, SIRT1 could promote prostatic intraepithelial neoplasia lesion formation through repressing androgen responsive gene expression and consequently inducing autophagy." (PMID 21698133, 2011). "However, SIRT1 expression is increased in human prostate cancer tissues, compared with adjacent normal prostate tissues, and SIRT1 promotes prostate cancer by deacetylating and inactivating FOXO1 protein and by protecting cells against oxidative stress." (PMID 21698133, 2011).